CD83 (CD83 molecule)
Diseases named in the same sentence as CD83 in open-access papers (continued):
Sharing a sentence is not in itself a finding about the gene and the disease.
colitis (continued). "Moreover, the authors reported that overexpression of CD83 on intestinal epithelial cells mitigated DC activation and thus, severity of colitis." (PMID 35054916, 2022). "In addition, analyses of Foxp3-specific cKO mice in a transfer colitis model affirmed that expression of CD83 not only on DCs but also on Tregs plays an important role in intestinal immune regulation and homeostasis in IBD." (PMID 32362900, 2020). "Studies have shown that knockout of CD83 in Tregs results in a more highly activated, pro-inflammatory phenotype and that CD83 knockout in the autoimmune animal models, EAE and colitis, consistently demonstrated a more severe disease course." (PMID 40777014, 2025). "Frequencies of CD83+ and CD80+ cells in the colitis group were increased compared to the control group (p < 0.01)." (PMID 39201260, 2024). "The probiotic mixture administered to mice with colitis reduced the frequencies of CD40+ (p < 0.001), CD83+ (p < 0.01), and CD80+ (p < 0.001) cells compared to untreated colitis mice." (PMID 39201260, 2024). "In this study, we showed that CD40+, CD83+, and CD80+ cells were decreased in IELs of colitis mice after probiotic mixture treatment." (PMID 39201260, 2024). "In IELs, administration of the probiotic mixture to mice with colitis also significantly decreased the frequencies of CD40+, CD83+, and CD80+ cells (p < 0.05)." (PMID 39201260, 2024). "Furthermore, ERAP1+/− colitis mice exhibited higher levels of CD40+, CD80+, and CD83+ cells compared to WT colitis mice." (PMID 40977735, 2025). "Similarly, inflamed colons of mice with colitis and patients with IBD show elevated levels of CD83+ and CD11c+ cells, respectively." (PMID 39201260, 2024). "Thereby, Treg-specific ablation of CD83 enhances autoimmune reactions, as demonstrated by elevated anti-nuclear antibodies, aggravated disease course in the EAE model as well as exacerbated colitis symptoms." (PMID 35054916, 2022). "In a murine colitis model induced by dinitrobenzene sulfonic acid (DNBS), an outstanding high number of CD83+ leukocytes infiltrated the inflamed GI tract and even more interestingly, colonic cell populations were demonstrated to release sCD83 upon disease occurrence." (PMID 32362900, 2020). "The data indicated that QCHS could reduce CD103+ DC numbers in the experimental colitis mice and decrease the frequency of MHC-II+CD83+ DCs and the levels of IL-12 ex vivo and in vivo, which suggests that QCHS inhibits DC maturation to form immature DCs." (PMID 32967687, 2020). "In the present study, the level of MHC-II was increased in DCs from the colitis mice without treatment along with over-expression of costimulatory molecules of DCs, including CD83, CD28, B7-DC, CD40, CD40 L, and TLR2." (PMID 27932984, 2016). "Similarly, elevated numbers of CD83+ cells have been reported in the inflamed colonic tissues of colitis mice and IBD patients, and CD11c+ cells are also upregulated in the inflamed mucosa and lamina propria of colitis models." (PMID 40977735, 2025). "Administration of T. halophilus to DSS-induced colitis mice significantly decreased the frequencies of CD83+ cells compared to non-treated colitis mice in PBL (12.33 ± 2.11% vs. 39.88 ± 8.91%, p < 0.001) and in IELs (44.63 ± 14.81% vs. 67.92 ± 1.10%, p < 0.01), respectively." (PMID 35741032, 2022).
autoimmune disease (11 papers, 2017 to 2025). A disorder resulting from loss of function or tissue destruction of an organ or multiple organs, arising from humoral or cellular immune responses of the individual to their own tissue constituents. "Alternatively, recombinant soluble extracellular CD83 constructs (rsCD83) mimicking the natural soluble (s)CD83 variant have demonstrated potent immunosuppressive properties in animal models of autoimmune disease and transplantation." (PMID 31231400, 2019). "Previous studies have shown that CD83 is a member of the immunoglobulin (Ig) superfamily, which is elevated in the serum of patients with autoimmune disease and hematological malignancies and has an immune suppressive function." (PMID 35189817, 2022). "This highlights the potential for anti-CD83 antibodies as a targeted therapy for autoimmune diseases." (PMID 35222372, 2022). "Similar dynamics have been described for antigen presenting cell maturation marker CD83, which is reported to be immunosuppressive in autoimmune diseases in its soluble form." (PMID 33190167, 2021). "On the other hand, the soluble CD83 protein has a great therapeutic potential to prevent/cure autoimmune disorders and to inhibit transplant rejection, via the induction of regulatory mechanisms, including Tregs and tolerogenic DCs." (PMID 32362900, 2020). "It has been suggested that the inhibition of CD83 mRNA transport can be applied to develop therapeutics for autoimmune diseases." (PMID 31582900, 2019). "In this review we discuss the recent biological findings and the potential clinical value of CD83 based therapeutics in various conditions including autoimmune disease, graft-vs.-host disease, transplantation and hematological malignancies." (PMID 31231400, 2019). "Soluble CD83 (sCD83), which is elevated in the serum of patients with autoimmune disease and some hematological malignancies is reported to have an immune suppressive function." (PMID 31231400, 2019). "Beyond the influence of membrane CD83 on lymphocyte function, an anti-inflammatory role of soluble CD83 was depicted in different models of autoimmune diseases as well as allograft transplantation." (PMID 28491062, 2017). "Additionally, CD83 is an activation marker for antigen presenting cells, and soluble CD83 is reported elevated in the serum of patients with autoimmune disease and some hematological malignancies with an immune suppressive function." (PMID 40659985, 2025). "Although CD83 has been involved in immunological responses, its functions in autoimmune diseases and effects on pathogen immune evasion remain unclear." (PMID 36769151, 2023). "Collectively, further exploration of the potential of CD83 as a “pro-resolution” therapy may provide modern healthcare with an interesting tool to combat chronic and autoimmune diseases as well as to improve transplant acceptance." (PMID 35054916, 2022). "However, the manipulation of the CD83 pathway has been proposed to develop therapeutics for the treatment of inflammation and autoimmune diseases." (PMID 31582900, 2019). "In addition, the application of modified CD83 molecules could be a promising strategy for treating inflammatory and autoimmune diseases." (PMID 36769151, 2023). "Another group showed that a mouse anti-human CD83 mAb could deplete DC and restrain self-reactive T cell generation in a xenograft temporal-artery plus PBMC SCID mouse model of autoimmune vasculitis indicative of potential utility for anti-CD83 treatment in autoimmune diseases." (PMID 35222372, 2022). "To investigate the role of endogenous human CD83 expression under inflammatory condition in vivo, we used the EAE model, which is an animal model for T-cell-mediated autoimmune diseases." (PMID 31293592, 2019).
Autoimmunity (11 papers, 2018 to 2026). The occurrence of an immune reaction against the organism's own cells or tissues. "These antibodies showed biased immunoglobulin V-domain usage, linked to a CD69/CD83 plasma cell state associated with disease severity and degree of autoimmunity." (PMID 41646792, 2026). "CD83 can function as a regulatory molecule that plays a pivotal role in autoimmunity and autoinflammation through various mechanisms to reduce inappropriate immunological responses." (PMID 36769151, 2023). "One is CD83, which helps orchestrate the balance between protective immunity and harmful autoimmunity." (PMID 37834915, 2023). "Recombinant CD83 proteins and anti-CD83 antibodies that exploit the function of CD83 were demonstrated to be effective in the treatment of various mouse models of autoimmune and inflammatory diseases (such as graft rejection, RA, and inflammatory bowel disease)." (PMID 37232738, 2023). "Microparticles enhance CD83 marker expression and induce autoimmunity in SLE patients." (PMID 36769151, 2023). "Moreover, we identified CD83 as another candidate target gene for SLE and studies have found soluble CD83 to be a promising therapeutic to interfere with autoimmunity in SLE38." (PMID 36750564, 2023). "It is of great interest to determine if anti-CD83 antibodies could be therapeutic in other inflammatory settings involving activated DC such as solid organ transplant rejection or autoimmunity." (PMID 31231400, 2019). "In particular, the membrane bound form of CD83 is absolutely essential for the development of CD4+ T cells and inhibits autoimmunity via the induction of regulatory mechanisms which dampen ongoing or overshooting immune responses." (PMID 32362900, 2020). "The dependency between the percentage of HLA-G+ DC-10 and the percentage of CD83+ DC-10 was also detected in HCs (p = 0.0069) but not in Abpos FDRs or T1D patients (subjects with autoimmunity)." (PMID 34659254, 2021). "Interestingly, the monitoring of the myeloid compartment, and, in particular, of CD83+ DC-10, might be used to follow changes in the immunological status from the absence of signs of autoimmunity to the overt disease." (PMID 34659254, 2021).
COVID-19 (11 papers, 2021 to 2025). A disease caused by infection with severe acute respiratory syndrome coronavirus 2. "The response to agonist stimulation was also greatly limited in pDCs from severe COVID-19 patients compared to healthy donors and patients with mild symptoms/asymptomatic, notably as shown by the level of activation markers (CD83, CD80, and PD-L1; red arrows)." (PMID 36755036, 2023). "The dysregulation of DC function in COVID-19 was also presented by the expression of the maturation marker (CD83), T-cell stimulation molecules (CD40, CD80, CD86) and antigen presentation molecules (HLA-DQA2 and FCER1A)." (PMID 34502134, 2021). "Compared to mild cases, severe COVID-19 showed upregulated CD40 together with downregulated CD83, HLA-DQA2 and FCER1A in all three tissues." (PMID 34502134, 2021). "In the delayed pattern at seven days after admission for COVID-19, significant differences were appreciated in serum levels of CD83, KRLD1, VEGFA, NCR, TNFSR24, PD-L2, and IL-12." (PMID 34177897, 2021). "Similarly, dendritic cells (DCs) from COVID-19 patients had weaker baseline expression of maturation markers CD83 (MMR 0.75) and HLA-DR (MMR 0.59, p = 0.018), along with a trend toward reduced expression of pattern recognition receptors (PRR) CD284/TLR4 (MMR 0.29) and Dectin-1 (MMR 0.62)." (PMID 36052094, 2022). "In line with our findings, CD14hiCD16hi cells and AMs enriched with viral RNA in autopsy lungs of COVID-19 patients also had distinct transcriptomes which were largely recapitulated in what we construe as CXCL10-associated genes (CXCL11, CCL18, CCL8, ISG15, CD83)." (PMID 35483404, 2022). "In a large, prospective, multicenter cohort, we find that either a single gene, OLAH, or a combination of 3 genes, CD83, ATP1B2, and DAAM2, accurately predicted 28-day mortality in hospitalized patients with COVID-19, including those who have been vaccinated." (PMID 41212055, 2025). "We then compared CD3+ cells isolated from COVID-19-infected subjects vs. healthy controls and found increased expression of activation markers including CD69, CD83, ICOS, RGS1 as well as other stress related genes including HIF1A, ATF4, NFKB1, and PR1." (PMID 36881624, 2023). "In lung, CD40, CD80, CD83 and HLA-DQA2 were upregulated while CD86 and FCER1A were decreased in mild COVID-19 as compared to healthy controls." (PMID 34502134, 2021). "COVID-19 can induce cytokine storms, such as IL6, IL32, CD83, CCL2, CXCL11, the TNF family (TNFSF9 and the receptor TNFRSF9), and integrin-related genes, which exacerbates COVID-19 related myocarditis and decreases the prognosis of patients requiring ECMO treatment." (PMID 39026189, 2024). "Expectedly, increasing COVID-19 severity had a modest negative effect on most surrogates of innate immune cell activation and maturation, most notably on CD83 upregulation (ρ = -0.53)." (PMID 36052094, 2022). "In sharp contrast, pDCs from severe COVID-19 patients failed to be activated by SARS-CoV-2-infected cells, as demonstrated by the absence or low detection of IFN-α, IFN-λ, CD83, and CD80/PD-L1 as compared to healthy donors and mild/asymptomatic patients (red bars and arrows)." (PMID 36755036, 2023).
viral infection (11 papers, 2011 to 2025). "In our experimental conditions, the virus infection induced CD83 expression only transiently, and the expression level returned to the basal level within 24 h post-infection." (PMID 33302987, 2020). "We analyzed cells of the peritoneal cavity, splenocytes, and cells of the bone marrow with FACS to investigate CD83 expression and cell population change in response to the virus infection." (PMID 33302987, 2020). "Consequently, HSV targets CD83 activity directly or indirectly, emphasizing the critical function of viral proteins and CD83 molecules during the activation of immunological responses and participation in the treatment of severe viral infections." (PMID 36769151, 2023). "The multitude of distinct virus families, which have independently evolved strategies to directly or indirectly target CD83 expression, underscores the vital role of CD83 during the activation of immune responses and thus the involvement in controlling (persistent) viral infections." (PMID 32362900, 2020). "The lower number of the CD4+ T cell population in the CD83 KO mice could also have affected the antibody production efficacy after virus infection." (PMID 33302987, 2020). "HSV-1 infection also suppresses de novo expression of CD83 through degradation of cellular mRNA during DC maturation and blocks CD83 mRNA export from the nucleus into the cytoplasm, implying the importance of knocking out this protein for viral infection." (PMID 23424672, 2013). "In viral bacterial challenge, when MoDCs were treated with 5 × 106 CFU heat killed pneumococci at 0 hr or 6 hr after virus infection, the expression of CD83 was comparable to that in pneumococcal stimulated MoDCs, but it was significantly higher than that in virus infected MoDCs." (PMID 21771345, 2011). "Because B cell function is important to combat virus infection, we investigated the modulation of the B cell and T cell population at different time points after influenza A virus infection and confirmed the requirement of CD83 in the virus-specific antibody production using CD83 knockout (KO) mice." (PMID 33302987, 2020). "The viral infection inhibited the expression of cell maturation surface markers (CD40, CD80 and CD83) and MHCI, and impaired the ability of P3-infected DCs for activating allogeneic naïve T cells." (PMID 21269456, 2011). "While often shown to increase with non-virally-mediated DC activation, CD83 tends to remain unchanged or even decrease with viral infections, including RV." (PMID 25584821, 2015). "This HSV-2 infected moDCs showed decreased levels of CD83 expression and other co-stimulatory molecules with increased levels of cytokines and proteins such as TNF-α, IL-6, and CCL3, further enhancing weaker T cell responses and other immunodeficiencies to viral infection." (PMID 36769151, 2023). "Downregulation of CD83 is, however, not an unusual consequence of virus infection of DCs." (PMID 26575844, 2015).
Crohn disease (8 papers, 2012 to 2024). A gastrointestinal disorder characterized by chronic inflammation involving all layers of the intestinal wall, noncaseating granulomas affecting the intestinal wall and regional lymph nodes, and transmural fibrosis. "An increase in CD83 expressing DC has been observed in patients with Crohn’s disease and in patients with rheumatoid arthritis." (PMID 33868228, 2021). "Different pathophysiological models provide insight into the important role of CD83+ dendritic cells (DCs) in the pathogenesis of Crohn’s disease (CD) and ulcerative colitis (UC)." (PMID 32572123, 2020). "A significant number of CD83-expressing DCs have been observed in patients with Crohn's disease." (PMID 31582900, 2019). "The Newcastle University RA (Dex + Vit D3) and the Crohn’s disease (Dex) trials both reported decreased CD83 expression, high CD86 expression, decreased IL-12 secretion, and elevated IL-10 secretion in their tDC products suggesting a possible tDC shared phenotype." (PMID 29075262, 2017). "Similarly, immunohistochemistry analysis in Crohn’s disease and ulcerative colitis patients showed the levels of activation markers like CD83 and CD86 expressed on DCs, primarily mDCs, were significantly higher in inflamed mucosa from patients compared with non-inflamed mucosa and healthy controls." (PMID 38448477, 2024). "The Crohn’s disease group had only 3 subjects without CD83+ DS, 15 subjects with one CD83+ DS and 26 subjects with CD83+ DS = 2–10." (PMID 38610835, 2024). "In the lesions of Crohn's disease, the numbers of CD83+ DC and DC-specific ICAM-3 grabbing nonintegrin (DC-SIGN)+ populations are significantly increased, while IL-12 and IL-18 are only detected in DC-SIGN+ DC and not in CD83+ DC." (PMID 31886308, 2019). "Tol-DCs generated from Crohn’s disease patients showed a statistically significant impairment in the upregulation of CD80, CD83 and HLA-DR compared to iDCs, with no CD86 modification." (PMID 23300676, 2012).
influenza (7 papers, 2012 to 2025). An acute viral infection of the respiratory tract, occurring in isolated cases, in epidemics, or in pandemics; it is caused by serologically different strains of viruses (influenzaviruses) designated A, B, and C, has a 3-day incubation period, and usually lasts for 3 to 10 days. "Antibody blocking CD83 prevents NA access, or soluble CD83 decoy NA, can mitigate cytokine storms, reduce lung injury induced by the influenza virus, and alleviate influenza symptoms." (PMID 37641134, 2023). "CD83 expression has been also shown to be important for anti‐influenza antibody production in the serum, and this may relate to the higher antibody titer that has often been reported in people with more severe disease." (PMID 36353774, 2023). "Surface expression of CD83, CD86 and HLA-DR in all influenza nanoparticle construct-treated conditions were significantly higher (P <0.05) than that of all soluble protein conditions at both time points." (PMID 32760143, 2020). "Like in NP-OVA immunized mice and in human tonsils, we saw more CD83 and CD86 on WT CXCR4lo centrocytes than on CXCR4hi centroblasts during influenza infection." (PMID 24184055, 2013). "Delays in the upregulation of CD83 and CD86 were seen, compared to Influenza, which is a robust activator of pDCs." (PMID 22693567, 2012).